ILF2 (interleukin enhancer binding factor 2)
Diseases named in the same sentence as ILF2 in open-access papers (continued):
Sharing a sentence is not in itself a finding about the gene and the disease.
liver cancer (continued). "In order to reduce the expression of ILF2 and CREB in two liver cancer cells, ILF2- or CREB-specific shRNAs were used." (PMID 30881868, 2019). "To understand the expression of two proteins in liver tissues, we detected mRNA levels of CREB and ILF2 and observed that CREB and ILF2 mRNA levels were upregulated in liver cancer tissues compared to adjacent normal tissues." (PMID 30881868, 2019). "However, the exact mechanism of ILF2 in liver cancer is almost unknown." (PMID 30881868, 2019). "Here, we found that ILF2 directly bound with CREB, and this binding was essential for the malignant phenotypes of liver cancer cells." (PMID 30881868, 2019). "In this study, we discovered the aberrant expression of ILF2 in HCC, and its regulation of liver cancer cell proliferation, cell growth, and apoptosis." (PMID 27556459, 2016). "Therefore, our results indicate that ILF2 expression is upregulated in both HCC tissues and liver cancer cell lines, and upregulation of ILF2 occurs via transcription and not via protein turnover." (PMID 27556459, 2016). "qPCR validation in normal liver and HCC tissues showed that CCNA2, CSRP2, ILF2, KIF2C, RACGAP1, and VARS were significantly upregulated in the HCC group (all p-values < 0.0001), providing more evidence for their role in liver cancer progression and potential as HCC biomarkers." (PMID 41323394, 2025). "In addition, ILF2 directly binds to cyclic adenosine monophosphate response element-binding protein (CREB), and this binding is essential for the malignant phenotypes of liver cancer cells." (PMID 35433409, 2022). "Moreover, increased protein expressions of CREB and ILF2 were found in liver cancer tissues compared to adjacent normal tissues." (PMID 30881868, 2019). "Then we tested whether ILF2 and CREB are essential in the process of liver cancer development." (PMID 30881868, 2019). "As for ILF2, its direct downstream stimulators in liver cancer have not been reported until now." (PMID 30881868, 2019).
lung carcinoma (5 papers, 2020 to 2025). "ILF2 is upregulated in several malignancies, including liver and lung cancer, where its high expression stimulates malignant phenotypes in liver cells and interacts with E2F transcription factor 1 (E2F1) to promote lung cancer progression." (PMID 38622522, 2024). "Although the dysregulation of ILF2 is involved in multiple cancer types, its role in lung cancer is unclear." (PMID 38303720, 2024). "Although the dysregulation of ILF2 is involved in multiple cancer types, its role in lung cancer remains unclear." (PMID 38303720, 2024). "Thus, it is of interest to determine the role of ILF2 in lung cancer development and in mediating the function of the PRMT1/PRMT6 heteromer in vivo." (PMID 38303720, 2024). "Taken together, our results suggest that the increased expression of ILF2 by the PRMT1/PRMT6 heteromer promotes cell proliferation and likely contributes to lung cancer health disparities in Black/AA men." (PMID 38303720, 2024). "However, the in vivo role of ILF2 in driving lung cancer and whether the function of PRMT1/PRMT6 heteromer is mediated via ILF2 still await further investigation." (PMID 38303720, 2024).
esophageal cancer (4 papers, 2016 to 2024). A primary or metastatic malignant neoplasm involving the esophagus. "Nicotine promotes the stabilization and expression of SALL4 by upregulating the RNA-binding protein interleukin enhancer binding factor 2 (ILF2), which facilitates tumor initiation in esophageal cancer cells." (PMID 38584262, 2024). "Indeed, we found that the mRNA expression levels of ILF2 and YBX1 were upregulated in esophageal carcinoma tissues compared to normal controls in GEPIA dataset." (PMID 36717549, 2023).
pancreatic carcinoma (4 papers, 2018 to 2025). "A first key finding was the discovery that the curcumin treatment of pancreatic carcinoma cells suppressed interleukin enhancer binding factor 2 (ILF2) overexpression, which regulated EMT-associated genes in this type of cancer." (PMID 35873564, 2022). "For instance, miR-7 has been demonstrated to function as a tumor-suppressor gene in pancreatic carcinoma via regulation of ILF2." (PMID 29614984, 2018). "Additionally, upregulation of ILF2 was also testified to exacerbate cell invasion and metastasis in melanoma and to regulate EMT-related genes in pancreatic cancer PANC-1 cells." (PMID 35333683, 2022).
melanoma (3 papers, 2021 to 2022). A malignant, usually aggressive tumor composed of atypical, neoplastic melanocytes. "Our study uncovered that ILF2 amplification of the 1q21.3 chromosome is associated with melanoma progression and triggers a functional downstream pathway in metastatic melanoma promoting drug resistance." (PMID 34709752, 2021). "Our results demonstrated that ILF2 expression is associated with 1q21.3 amplification and melanoma progression." (PMID 34709752, 2021). "In this study, we found that 1q21.3 amplification‐driven ILF2 upregulation is associated with melanoma progression." (PMID 34709752, 2021). "• ILF2 expression is associated with 1q21.3 amplification and melanoma progression." (PMID 34709752, 2021). "Additionally, ILF2 expression is significantly increased with melanoma progression (p < .0001), and significantly associated with poor overall survival for metastatic melanoma patients (p = .026)." (PMID 34709752, 2021). "Consistent with a decreased cell proliferation, melanoma cells with ILF2 depletion underwent cell cycle arrest in the G1 phase (p < .05) and showed decreased expression for CHK2, which is a critical checkpoint factor for cell cycle." (PMID 34709752, 2021). "Our studies showed that ILF2 levels were significantly increased during melanoma progression and positively correlated with gene CNV." (PMID 34709752, 2021). "ILF2‐OV melanoma cells treated with the ATMi KU‐55933 showed reduced cell proliferation than the respective control EV cell lines." (PMID 34709752, 2021). "To identify the downstream pathway controlled by ILF2 that increases DDR, we compared the two metastatic melanoma cell lines with ILF2‐OV to their respective control cell lines using RPPA analysis." (PMID 34709752, 2021). "To summarise, melanoma cell lines with reduced ILF2 expression treated with TMZ are more sensitive to DNA damage and display enhanced accumulation of DSB." (PMID 34709752, 2021). "In invasion assays, melanoma cells with ILF2‐OV showed a higher percentage of invasion (35.6% in DP‐0574 and 26.3% in IM‐0223) compared to control EV cells (8.5% in DP‐0574 and 10.3% in IM‐0223)." (PMID 34709752, 2021). "More importantly, ILF2 or U2AF2 downregulation increased the sensitivity to the DNA‐damage agent TMZ in metastatic melanoma cells." (PMID 34709752, 2021). "ILF2 mRNA average level showed a 2.24 fold‐change enhancement in primary melanomas compared to normal skin tissues (p < .0001)." (PMID 34709752, 2021). "Functional assays revealed a regulatory role for ILF2 in promoting cell proliferation and colony formation, which further raises the question of what downstream factors are regulated by ILF2 to promote melanoma tumour progression." (PMID 34709752, 2021). "Along with the elevated RAD50 expression, enhanced ATM and increased p‐ATM levels were observed in metastatic melanoma cells with ILF2‐OV." (PMID 34709752, 2021). "Metastatic melanoma patients with high ILF2 mRNA expression had shorter OS time compared to patients with low ILF2 mRNA expression (p = .026)." (PMID 34709752, 2021). "Using the SJCI's microarray dataset, enhanced ILF2 mRNA levels were also observed in metastatic melanoma cell lines compared to melanocytes (p < .01)." (PMID 34709752, 2021). "In summary, ILF2 expression levels significantly correlate with melanoma cell proliferation, colony formation and invasion rates." (PMID 34709752, 2021). "All these observations were consistent with the results of RNA in situ hybridisation (RNA ISH) for ILF2 mRNA expression in melanoma FFPE tissues." (PMID 34709752, 2021). "Metastatic melanoma cell lines with ILF2‐OV showed higher proliferation rates compared to empty vector (EV) control cell lines (p < .001 and p < .001, respectively)." (PMID 34709752, 2021). "Metastatic melanoma cell lines (DP‐0574 and IM‐0223) were selected to perform ILF2 overexpression (ILF2‐OV) based on the relative expression levels of ILF2." (PMID 34709752, 2021).
melanoma (continued). "Consistently, the tumour tissues from stage III and IV metastatic melanoma patients had significantly increased ILF2 protein average levels (1.56 and 1.62 fold‐change, respectively) compared to the primary melanoma tissues." (PMID 34709752, 2021). "Additionally, stage III melanoma patients with high ILF2 mRNA expression had significantly higher U2AF2 mRNA levels compared to patients with low ILF2 mRNA expression (p < .05)." (PMID 34709752, 2021). "The results showed that ILF2 interacts with U2AF2 in the nucleus of metastatic melanoma cell lines." (PMID 34709752, 2021). "Interestingly, higher sensitivity to ATMi was observed in melanoma cell lines with ILF2 overexpression." (PMID 34709752, 2021). "To determine whether decreased ILF2 expression reduced cell proliferation, we selected two metastatic melanoma cell lines (IM‐0223 and M‐204) to generate stable knockdown for ILF2." (PMID 34709752, 2021). "Melanoma cell lines with ILF2 overexpression activate a more effective DNA damage response to TMZ." (PMID 34709752, 2021). "Melanoma cells with ILF2‐OV showed a significant upregulation in ATM mRNA levels." (PMID 34709752, 2021). "Four stable melanoma cell lines were established for in vitro ILF2 functional characterisation." (PMID 34709752, 2021). "Additionally, ILF2 knockdown significantly induced late apoptosis in melanoma cells (p < .001)." (PMID 34709752, 2021). "In cell viability assays, metastatic melanoma cell lines with ILF2 knockdown had increased sensitivity to TMZ (p < .0001), while metastatic melanoma cell lines with ILF2‐OV showed increased resistance to TMZ (p < .0001)." (PMID 34709752, 2021). "While ILF2‐OV induced the upregulation of RAD50, U2AF2 knockdown decreased the RAD50 protein levels in ILF2‐OV melanoma cells." (PMID 34709752, 2021). "Moreover, ILF2 and U2AF2 mRNA levels had a significant positive correlation in melanoma (primary and metastasis) tumour samples from TCGA SKCM dataset (r = 0.12, p = .008)." (PMID 34709752, 2021).
mesenchymal tumors (3 papers, 2022 to 2024). "In mesenchymal tumors, circPOK regulates pro-proliferative and pro-angiogenic factors by acting as a coactivator of ILF2/3 upon ILF2/3 binding to the proximal promoter of II6." (PMID 36506086, 2022). "circPOK interacts with ILF2/3 complex to promote Il6 transcription in mesenchymal tumors." (PMID 36747292, 2023).
pancreatic ductal adenocarcinoma (3 papers, 2016 to 2023). An infiltrating adenocarcinoma that arises from the epithelial cells of the pancreas. "Moreover, a recent report has indicated a close correlation between ILF2 expression and tumor size in pancreatic ductal adenocarcinoma (PDAC) and that ILF2 could be a valuable prognostic indicator for survival in PDAC patients." (PMID 27556459, 2016).
breast tumor (2 papers, 2019 to 2024). "Furthermore, using three GEO datasets (GSE100534, GSE148283, and GSE173661), we found that ILF2 was more highly expressed specifically in BCBrM sites than in primary breast tumours, brain tumours in situ and other metastatic sites, such as the lung, liver, and kidney." (PMID 38943472, 2024).
psoriasis (2 papers, 2022 to 2023). An autoimmune condition characterized by red, well-delineated plaques with silvery scales that are usually on the extensor surfaces and scalp. "Overexpression of KLHDC7B-DT in psoriasis was related to the aberrant expression of ILF2." (PMID 35586566, 2022). "We found that the expression levels of KLHDC7B-DT, as well as its binding protein ILF2, were upregulated in both skin lesions and psoriasis model keratinocytes, suggesting that KLHDC7B-DT and ILF2 might be involved in the pathogenesis of psoriasis." (PMID 35586566, 2022). "The expression of KLHDC7B-DT and ILF2 was focused only on psoriasis." (PMID 35586566, 2022). "However, little is known about the role of ILF2 in psoriasis." (PMID 35586566, 2022). "Furthermore, we found that ILF2 functions in a KLHDC7B-DT-dependent manner in psoriasis." (PMID 35586566, 2022). "Here, we explored the role of ILF2 and KLHDC7B-DT in the pathogenesis of psoriasis for the first time." (PMID 35586566, 2022). "ILF2 and KLHDC7B-DT were involved in the hyperproliferation of keratinocytes and skin inflammation in psoriasis." (PMID 35586566, 2022).
triple-negative breast carcinoma (2 papers, 2023 to 2024). An invasive breast carcinoma which is negative for expression of estrogen receptor (ER), progesterone receptor (PR), and human epidermal growth factor receptor 2 (HER2). "Our study revealed that the LINC00571/HNRNPK/ILF2/IDH2 axis promoted the progression of triple-negative breast cancer by regulating tricarboxylic acid cycle metabolites." (PMID 38238853, 2024).
adenoma (1 paper, 2024). A neoplasm arising from the epithelium. "By comparing the gene expression in adenomas and colorectal cancer tissues, they found that ILF2 gene expression was more closely associated with the progression from adenoma to carcinoma than with inflammatory bowel disease." (PMID 39735599, 2024).
arteritis (1 paper, 2018). An inflammatory process affecting an artery. "Furthermore, ILF2 autoantibodies were exclusively found in ANAS sera; they were not present in sera from the 84 healthy controls or in the 57 patients with IMRD ANAH, IMRD without ANA, or with steroid-responsive meningitis-arteritis." (PMID 29556082, 2018).
autoimmune disease (1 paper, 2018). A disorder resulting from loss of function or tissue destruction of an organ or multiple organs, arising from humoral or cellular immune responses of the individual to their own tissue constituents. "While ILF2 and ILF3 autoantibodies are a common finding in dogs with autoimmune diseases, our screening of human sera is in line with previous reports that ILF2 and ILF3 autoantibodies are only occasionally present in humans." (PMID 29556082, 2018). "Furthermore, ILF2 and ILF3 autoantibodies were present in human patients with autoimmune disease, but as a rare finding." (PMID 29556082, 2018).
colorectal cancer (1 paper, 2024). A primary or metastatic malignant neoplasm that affects the colon or rectum. "This indicates that ILF2 could be instrumental in detecting colorectal cancer at an early, more treatable stage." (PMID 39735599, 2024).
COVID-19 (1 paper, 2023). A disease caused by infection with severe acute respiratory syndrome coronavirus 2. "The interferon (IFN)-stimulated 15 KDa protein (ISG15) had the largest increase in serum of COVID-19 patients, followed by several other IFN-induced proteins, such as ILF2, MX1, ISG20, LAP3, and UBE2L6." (PMID 37739942, 2023).
cutaneous melanoma (1 paper, 2021). A primary melanoma arising from atypical melanocytes in the skin. "To summarise, ILF2 mRNA and protein expression are increased during cutaneous melanoma progression due to ILF2 gene amplification." (PMID 34709752, 2021). "Interleukin enhancer‐binding factor 2 (ILF2) is located in the 1q21.3 amplified region, but its functional role or contribution to tumour aggressiveness in cutaneous melanoma is unknown." (PMID 34709752, 2021).
diabetes (1 paper, 2024). "The results revealed the same changing trend of gene expression in diabetes, although the alteration of the serum protein level of ILF2 was not significant." (PMID 39553470, 2024).
endometrial cancer (1 paper, 2025). Primary or metastatic malignant neoplasm involving the endometrium (mucous membrane that lines the endometrial cavity). "Some DNA-binding proteins such as heterogeneous nuclear ribonucleoprotein L (HNRNPL), heterogeneous nuclear ribonucleoprotein U (HNRPU), and interleukin enhancer binding factor 2 (ILF2) are closely associated with endometrial cancer." (PMID 40575382, 2025).
hepatic (1 paper, 2022). "The expression of Rbbp4, Tcea1, and ILF2 were significantly downregulated in significant hepatic-steatosis NAFLD patients compared to non-significant hepatic-steatosis controls." (PMID 35637971, 2022).
lung adenocarcinoma (1 paper, 2024). A carcinoma that arises from the lung and is characterized by the presence of malignant glandular epithelial cells. "Mutations within the ILF2 promoter associated with increased expression were identified in a subset of lung adenocarcinoma without RTK/RAS/RAF pathway alterations." (PMID 38303720, 2024).
lupus (1 paper, 2018). "Autoantibodies to ILF2 and ILF3 have previously been described in mice with induced lupus and as a rare finding in humans with autoimmune disease." (PMID 29556082, 2018).
lymph node metastasis (1 paper, 2017). "High expression of ILF2 was tightly correlated with depth of invasion, lymph node metastasis, pathological stage, and histological differentiation." (PMID 28831206, 2017). "The result revealed that the high expression of ILF2 was significantly related to histological differentiation, TNM stage, depth of invasion (T classification), and lymph node metastasis; moreover, the more advanced the tumor was, the higher possibility the overexpression of ILF2 existed." (PMID 28831206, 2017).